MRC1 (mannose receptor C-type 1)
Diseases named in the same sentence as MRC1 in open-access papers (continued):
Sharing a sentence is not in itself a finding about the gene and the disease.
cancer (529 papers, 2001 to 2026). A tumor composed of atypical neoplastic, often pleomorphic cells that invade other tissues. "Cancer cell CM upregulated expression of M2 markers Mrc1 (CD206), Arg1 and Mgl2 in macrophages, but infection reduced it." (PMID 40547518, 2025). "TAMs expressing the multi-ligand endocytic receptor mannose receptor (CD206/MRC1) have been suggested as a promising therapeutic target for cancer therapy." (PMID 32521802, 2020). "Co-culture of macrophages and cancer cells results in an initial switch to a phenotype characterized by high expression of IL-1β and IL-10, while an MRC1 expression remains unmodified." (PMID 31697737, 2019). "The 8 cell types were annotated based on the differentially expressed markers: Bnip3 for autophagic cancer cells, Mki67 for proliferating cancer cells, Cd14, Apoe, C1qc, Mrc1, Lyz2 for monocytes, Col3a1 for fibroblasts, Cd3e and Gzma for T cells, Flt1 for endothelial cells, and Klk1 for DCs." (PMID 38802348, 2024). "EVs generated by cancer cells promoted the polarization of macrophages to an inflammatory phenotype, characterized by the upregulation of several M1-associated genes (IL-1β, IL-8, CCL2, CXCL2) and the downregulation of MRC1 expression, an M2-related marker." (PMID 28600520, 2017). "Next, we evaluated the correlation between the DNA methylation and mRNA expression of CLEC5A and immune-related gene (MRC1, CD163, CD8A, CD8B, CD68) in pan-cancer." (PMID 35979347, 2022). "The pie chart showed that the heterozygous CNVs of all 6 genes (CD68, MRC1, CD8A, CD8B, CD163, and CLEC5A) was more frequent in various cancers." (PMID 35979347, 2022). "GSCALite was utilized to identify the SNV frequency of all 6 genes (CD68, MRC1, CD8A, CD8B, CD163, and CLEC5A) in various cancers." (PMID 35979347, 2022). "Because both analyses showed that OLFML2B was positively correlated with macrophage content, we input cancer-related macrophage markers into the web tool “CellMarker” and obtained experimentally verified markers: CD14, CD68, CD163, CSF1R, ITGAM, and MRC1." (PMID 34868901, 2021). "Mannose-containing molecules (mannose Mw: 180Da) can be used for cancer theranostics and vaccines to target the mannose receptor MRC1/CD206 which is overexpressed on pro-tumoral macrophages and also present on dendritic cells." (PMID 32069856, 2020). "Out of 52 genes investigated, we observed that many genes upregulated in M2 and downregulated in M1 macrophages–ACTN1, FLRT2, MRC1, PTGS1, RHOJ, TMEM158–correlated positively with the EMT scores (first 6 rows) across multiple cancer types." (PMID 30729096, 2019). "Furthermore, mannose receptor C type 1 (MRC1), also known as CD206, is a protein expressed on the surface of macrophages, a type of white blood cell that participates in the immune response to cancer." (PMID 37370832, 2023). "By bioinformatic analysis, we found that FAP was positively correlated to the expression of M2 macrophages marker MRC1 across gastrointestinal cancers, suggesting that FAP may be involved in regulating M2 macrophages in these cancers." (PMID 37325617, 2023). "Thus, the DNA methylation differences of CLEC5A and immune-related gene (MRC1, CD163, CD8A, CD8B, CD68) between tumors and normal tissues in various cancers were evaluated with the GSCALite platform." (PMID 35979347, 2022). "The pan-cancer analysis of single myeloid cells across 15 human cancer types unveiled significant findings, indicating that AMs express genes such as FABP4, MARCO, MRC1( also known as CD206), MSR1 and PPAR-γ, which are involved in self-replenishment through the secretion of (TGF-β." (PMID 38229178, 2024).
infection (178 papers, 2010 to 2026). The state of being infected such as from the introduction of a foreign agent such as serum, vaccine, antigenic substance or organism. "(E) In vitro infection of unpolarized (M0) bone-marrow-derived murine macrophages (BMDMs) resulted in a down-regulation of TRM-associated marker Mrc1 and an upregulation of M2-like markers Nos2 and Arg1." (PMID 38767331, 2024). "The immunosuppressive interaction of Ply with MRC-1 expressed on alveolar macrophages was confirmed in a murine model of experimental infection of the lower airways in which MRC-1-deficient mice exhibited a significant reduction in bacterial loads." (PMID 37446214, 2023). "Additionally, MRC1 expressed on M2 macrophages has been implicated as a mediator of the infection with virulent strains of some pathogens, such as Mycobacterium tuberculosis and Leishmania, increasing the severity of the disease." (PMID 39830895, 2024). "Notably, HM 1 and 2, and Cd14+ monocytes accounted for ~73% of all the microglia detected under homeostatic conditions, but IAMNP 1 and 2, and Mrc1+ BAMs subclusters progressively increased in frequency over the course of infection, suggesting an adoption of an infection-associated phenotype." (PMID 36180478, 2022). "We found that upon infection, there is an expansion of all the myeloid cells, but notably so within the Mrc1+ macrophage, Cd14+ monocyte and Cd207+ Langerhans cell subclusters." (PMID 37644007, 2023). "The TRMs from the eoCre: Il4/13f/f mice displayed significantly lower expression of Mrc1, Ccl24, and Tslp than WT mice after infection, whereas Il4r expression remained unchanged." (PMID 38030609, 2023). "Other myeloid cell types such as Cd14+ monocytes and Mrc1+ BAMs constitute additional responders to the infection, albeit with opposing effects; Cd14+ monocytes and Mrc1+ BAMs display pro- and anti-inflammatory phenotypes, respectively." (PMID 36180478, 2022). "The KDs included Mrc1 (response to infection), which is the only overlapping top KD between genotypes XXF and XXM." (PMID 35396276, 2022). "Violin plots show that Kp52145 infection increased the levels of the M(Kp) markers arg1, il10, chi3l1, ido, pparγ, mrc1, nos2, isg56 and il1rn (Fig EV5A–E)." (PMID 36337046, 2022). "Among the signaling cluster, significantly enhanced expression of Cd200, Camp, Chia1, Ctla2a, Dpep1, Mrc1, and Serpina1b was observed in the wild-type mice on day 7 post-infection." (PMID 34690967, 2021). "In the FISH probe test of the macrophages in the midbrain of control and RGNNV-injected fish, the Mrc1-positive signal was significantly increased after RGNNV infection, which also was consistent with our scRNA-seq result." (PMID 34185811, 2021). "In contrast, there was a significant reduction or failure in activation of type 2-related chemokines/cytokines (Cxcl12, Ccrl1, Il4, Il23a) and signature markers (Stat3, Stat5b, Stat6, Mrc1, Ahr) during infection." (PMID 34320039, 2021). "During infection by C. neoformans, mannose receptor C-type 1 (mrc1) was upregulated in both WT and Gal-3 KO mice compared to the control group." (PMID 34203011, 2021). "It was therefore proposed that the pneumococcus utilizes MRC‐1‐mediated uptake to persist intracellularly within DCs and macrophages in the lungs and utilizes them as Trojan horse to spread the infection." (PMID 31251447, 2019). "In contrast, these macrophages displayed a decreased expression of the M2 markers such as Arg1, Ym1, and Mrc1 (mannose receptor C-type 1) at 24 h post-infection." (PMID 31801478, 2019). "In contrast, some paired ligands and receptors, such as ANXA1_FPR1, C5AR1_RPS19, CCL5_CCR1, and PTPRC_MRC1, were significantly activated after infection, which may mediate the communication among T cells and myeloid cells." (PMID 37087411, 2023).
infection (continued). "have reported that infection of murine macrophages with a M. tuberculosis Beijing clinical isolate induced downregulation of MRC1 gene expression, suggesting that the repression of MRC1 expression favor M. tuberculosis infection." (PMID 34335572, 2021). "Interestingly, while JMJD3 was found to negatively regulate few of the mycobacteria-responsive M1 markers of macrophages viz., Il12, Il1b and Cxcl2, the expression of M2 markers like Arg1, Mrc1, Il10, Tgfb, Ccl17 and Ccl2 on infection were JMJD3-dependent." (PMID 27532872, 2016). "However, the infection dose is critical because low‐dose pneumococcal carriage induces immunoregulatory responses, characterised by a sustained elevation of nasopharyngeal TGF‐β1, regulatory T cells, and MRC‐1‐expressing macrophages in contrast to a high‐density infection." (PMID 31251447, 2019). "As infection progresses, DDX60+CHIT1hi Inflam‐Ms increase expression of key inflammatory markers, including HLA‐DRB1, MRC1, and SERPINE2." (PMID 41271590, 2026). "Elevated expression of multiple inflammatory genes, including IL6, TNF, IL10, and IL1B, were observed in the CD163+MRC1+TREM2 Mac and CD163+MRC1− subsets in both Cohort 1 and 2 after infection." (PMID 37024448, 2023). "While the upregulation of MRC1 and HMOX1 mRNA after infection was observed previously, we noted a downregulation of MRC1 and HMOX1 protein levels in moMΦ." (PMID 34835004, 2021). "Up-regulated levels were found for MRC1(Macrophage mannose receptor C type-1) and PRDX2 (Peroxiredoxin 2) following experimental infection with APP." (PMID 32632500, 2020). "DCs were infected with the unencapsulated strain T4R (to get better uptake than with encapsulated bacteria) or its isogenic PLY mutant T4RΔply and were immunostained for MRC‐1, pneumococci (anti‐serum), and the autophagy marker LC3B, at 3 h post‐infection." (PMID 32985105, 2020). "All of these results clearly showed that peripheral IgM+ B lymphocytes, but not CD3+ T cells and MRC1+ MØ, act as the primary target cells for the covert infection of MRV." (PMID 39772201, 2024). "Mannose receptor C-type 1 (MRC1), a meningeal macrophage marker, has been reported to bind to PLY, which downregulates inflammation and enhances bacterial survival at the infection site, while S. pneumoniae strain EF3030 has been detected in the trigeminal ganglion following nasal infection." (PMID 39345124, 2024). "Interestingly, at this early stage of infection, we did not identify any MRC1-, i.e., interstitial macrophage (IM) populations." (PMID 40742121, 2025). "Stimulation with the conditioned supernatants of infected dying cells (containing putative DAMP, cytokines produced by epithelial cells, extracellular vesicles, and released virions) or direct infection with SARS-CoV-2 did not induce MRC1 transcription or surface expression in macrophages." (PMID 35666101, 2022). "In the absence of injury or infection, most macrophages residing in human and mouse SKM were shown to be MRC1 (CD206)+, M2-like macrophages." (PMID 36259488, 2022). "Finally, we siRNA-depleted MRC1 (mannose receptor C type 1, CD206) transcripts from A549 cells and observed ~60% reduction in bacterial uptake after 1 h post-infection, relative to host cells treated with non-targeting siRNA." (PMID 28638804, 2017). "Consistent with the results from microarray experiments, PR/8 infection significantly decreased the mRNA levels of CLEC7A (Dectin 1), macrophage scavenger receptor 1 (MSR1), CD36, and the mannose receptor C type 1 (MRC1) but did not change the expression of MRC2." (PMID 22396727, 2012).
bacterial infection (11 papers, 2020 to 2025). "MRC1 and MRC2 are crucial components of the innate immune system, and they contribute to defense against pathogenic bacterial infections." (PMID 37340445, 2023). "We suggest that MRC‐1 peptides can be employed as adjunctive therapeutics with antibiotics to treat bacterial infections by countering the action of CDCs." (PMID 32985105, 2020). "In the current study, we demonstrate upregulation of Mrc1 in infected diabetic but not in control mice, thereby facilitating bacterial colonization and invasion, further supporting the impaired ability to control bacterial infections." (PMID 36127330, 2022).
colorectal (5 papers, 2010 to 2025). "Interestingly, LysMcreIl4ra−/lox liver granulomas retained expression of MMR and Ym1 in a subpopulation of macrophages, confirmed in mRNA and protein (Chi3l3) or protein (Mrc1) expression analyses." (PMID 20502521, 2010).
inflammation (5 papers, 2021 to 2025). Aberrant reaction of the microcirculation characterized by movement of fluid and leukocytes from the blood into extravascular tissues. "MiR-511-3p, encoded by the Mrc1/CD206 gene, has also been proven to reduce cockroach allergen-induced lung inflammation and promote M2 macrophage polarization by targeting CCL2 via the RhoA/ROCK axis or prostaglandin D2 synthase (Ptgds)." (PMID 37138859, 2023).
infectious disease (2 papers, 2019 to 2022). A disorder directly resulting from the presence and activity of a microbial, viral, or parasitic agent in humans. "Laiwu pigs were also reported to possess resistance to additional infectious diseases, including porcine circovirus type 2 infection, through the increased expression levels of mannose receptor C type 1 in the liver, kidney, and mesenteric lymph nodes." (PMID 36190425, 2022).
MRC1 also shares sentences with these, for which no sentence is quoted: Lynch syndrome (205 papers); endometrial cancer (58); gastric cancer (37); hereditary nonpolyposis colorectal carcinoma (30); renal fibrosis (26); hepatocellular carcinoma (23); ischemic stroke (19); Insulin resistance (18); liver fibrosis (15); rheumatoid arthritis (14); adenoma (12); Cerebral ischemia (12); lymph node metastasis (12); sarcoma (12); psoriasis (11); cervical carcinoma (10); Granuloma (10); kidney disease (10); lung adenocarcinoma (9); Arthritis (8); colorectal tumor (8); aneurysm (7); idiopathic pulmonary fibrosis (7); oral squamous cell carcinoma (7); polyposis (7); pulmonary tuberculosis (7); rectal cancer (7); triple-negative breast carcinoma (7); uterine cancer (7); Alzheimer disease (6).
A further 349 diseases each share a sentence with MRC1 in 6 papers or fewer.